IL6 (interleukin 6)
Diseases named in the same sentence as IL6 in open-access papers (continued):
Sharing a sentence is not in itself a finding about the gene and the disease.
E. coli infection (continued). "The reduced release of cyto-/chemokines by aged macrophages could explain the lower serum levels of IL-6 and KC in aged mice after intracerebral E. coli infection which we found in our mouse model." (PMID 25528768, 2014). "Centrally applied IL-6 decreases baroreceptor reflex sensitivity and thus may have contributed to the mechanism of increasing sympathetic activity to maintain perfusion pressure in the presence of systemic E. coli infection." (PMID 38331902, 2024). "Our results showed that E. coli infection triggered both a strong inflammatory response, via NF-κB pathway activation and pro-inflammatory cytokine (TNF-α, IL-6, IL-1β) release, and apoptotic cell death." (PMID 41302013, 2025). "L. fermentum MC018 reduced the levels of IL-1β, IL-6, and TNF-α in intestinal tissues following E. coli infection." (PMID 40963585, 2025). "In this study, E. coli infection resulted in elevated levels of TNF-α, IL-1β, and IL-6, accompanied by decreased IL-10 levels in the JM group, consistent with findings in animals induced with bacterial and Lipopolysaccharide challenges." (PMID 39199953, 2024). "The levels of IL-6, IL-8, and TNF-α expression in the endometrium of dairy cows were elevated 48 h post E. coli infection." (PMID 39409825, 2024). "Specifically, in vitro, pretreatment with MLA (50 μM) or MEM (50 μM) significantly attenuated the survival rates of HBMECs and reduced the expression of inflammatory cytokines (such as IL-6 and TNF-α) after E. coli infection." (PMID 36289622, 2022). "Our results showed that pretreatment with different doses of L. plantarum 17–5 reduced the expression of IL1β, IL6, IL8, TNFα, COX2, iNOS, CXCL2 and CXCL10 during E. coli infection." (PMID 35764986, 2022). "The levels of the inflammatory factors IL-2, IL-6, TNF-α, and MPO were significantly increased after E. coli infection, while MPX reduced the serum levels of IL-6 (p < 0.01), IL-2, TNF-α, and MPO (p < 0.05)." (PMID 34177825, 2021). "As expected, the levels of IL-6, TNF-α, IL-10, and the neutrophil chemoattractant keratinocyte-derived chemokine (KC) were increased in the sera of virgin control mice after E. coli infection." (PMID 33622714, 2021). "In parallel, the mRNA expression of IL-6 and TNF-α was detected in the PLCs collected from the mice infected with E. coli and treated with MS19 once at 1 h after E. coli infection." (PMID 28492513, 2017). "In the present study, E. coli infection activated NF‐κB predominantly through upregulation of TLR4 and accumulation of ROS, rather than through increased I‐κB phosphorylation, leading to elevated production of IL‐6 and TNF‐α." (PMID 41502826, 2026). "E. coli infection significantly induced PGE2 synthesis in BMDMs, which exacerbated the inflammatory response and tissue damage via NF-κB and MAPK signaling pathways, elevating TNF-α, IL-1β, IL-6, and IL-8." (PMID 40666730, 2025). "The expression levels of interleukin 1 b (IL1B), IL6, tumor necrosis factor a (TNFA), interleukin-8 (CXCL8), and defensin beta 2 (DEFB2) genes in the endometrium of the GE group were upregulated (p < 0.05) after E. coli infection." (PMID 40075974, 2025). "Moreover, the results demonstrate the expression of the cytokines IL-1β and IL-6, cell mediated responses as well as APEC-specific T-cell response dominated by IFN-γ-producing CD8α+ and TCR-γδ+ subsets to be triggered against colibacillosis." (PMID 37261344, 2023). "The results showed that XCHD could significantly reduce the concentrations of IL-1, IL-6 and TNF- α in infected chicks, indicating that XCHD can treat chicken colibacillosis by inhibiting systemic and pulmonary inflammation." (PMID 36678378, 2022). "Elevation of IL-6 mRNA expression within the first 24 hr post-CpG-ODN treatment in our study, particularly in the lungs, suggests its contribution to the immunological defence against E. coli infection." (PMID 32210244, 2020).
E. coli infection (continued). "Furthermore, the E. coli infection tended to increase the expression of TNF-α and IL-6 (P = 0.057 and P = 0.092, respectively)." (PMID 29948799, 2019). "In fact, at day 6 following C. jejuni infection, increased IFN-γ, TNF, IL-6 and MCP-1 serum levels could be measured (p<0.001), whereas E. coli infection resulted in elevated IFN-γ and TNF serum concentrations." (PMID 27438014, 2016). "Furthermore, the levels of IL-1β, IL-6, and TNF-α increase in mammary glands with E. coli infections in mice." (PMID 23626786, 2013). "At 3 h after E. coli infection, the qPCR results showed that overexpression of mgU2-30 led to a significant increase in the levels of pro-inflammatory cytokines IL-6, TNF-α, and IL-1β, whereas knockout of mgU2-30 did not cause an increase in the level of these cytokines in hBMECs." (PMID 34980188, 2022). "In these studies, E. coli infection increased the concentrations of pro-inflammatory cytokines (IFN-γ, TNF-α, IL-1β, IL-6 and IL-8) and decreased the concentrations of anti-inflammatory cytokine (IL-4), indicating that E. coli could induce inflammation in mice through regulation of cytokines." (PMID 33676495, 2021). "Additionally, in accordance with the previous study which showed that PD effectively inhibited the expression of proinflammatory cytokines including IL-1beta, IL-6, and TNF-alpha, PD treatment also decreased IL-8 and ICAM-1 induced by E. coli infection in our work." (PMID 32714880, 2020). "Although our study demonstrates increased IAP expression following E. coli infection, we did not evaluate TLR4 expression, proinflammatory cytokines (e.g., IL-6 and TNF-α), or NF-κB activation." (PMID 40804973, 2025).
endometrial cancer (72 papers, 2012 to 2025). Primary or metastatic malignant neoplasm involving the endometrium (mucous membrane that lines the endometrial cavity). "Endometrial cancer is linked to obesity and chronic inflammation, potentially mediated by adipocytokines like adiponectin, leptin, IL6, and TNFα." (PMID 40642843, 2025). "High IL-6 and IL-8 levels were independent risk factors for deep myometrial invasion in patients with endometrial cancer (p < 0.05)." (PMID 38464838, 2024). "Endometrial microbiota and their association with inflammatory cytokines, including IL-6, IL-8, IL-17, and mRNA, play a role in endometrial cancer." (PMID 38543097, 2024). "A high concentration of IL-6 in the serum of endometrial cancer patients is linked both with the carcinogenesis of the endometrium and with advancement of the cancer." (PMID 36834426, 2023). "A significant increase in risk of endometrial cancer was observed with elevated levels of C-reactive protein, interleukin 6 (IL-6), and interleukin 1 receptor antagonist (IL-1Ra)." (PMID 37175971, 2023). "The plasma concentrations of the proinflammatory cytokines TNF-α and IL-6 positively correlate with BMI, and, in turn, have been directly associated with endometrial cancer promotion and progression." (PMID 35053431, 2022). "The association between SNP in inflammatory pathway genes and endometrial cancer risk were conducted and found IL-6 SNP rs2069852 had an association with endometrial cancer risk." (PMID 33397383, 2021). "In conclusion, this study is novel in demonstrating the association between IL4, IL6 gene polymorphisms and susceptibility to endometrial cancer in Chinese Han women." (PMID 30828987, 2019). "We observed a significant increase in risk of endometrial cancer of rs1524107 (IL6) (T/C, OR = 1.61, 95% CI = 1.09–2.37, p = 1.55 × 10−2), rs2066992 (IL 6) (OR = 3.09, 95% CI = 2.11–4.53, p = 3.13 × 10−9)." (PMID 30828987, 2019). "In our study, we found that the association between IL6 gene polymorphisms and susceptibility to endometrial cancer in Chinese Han women." (PMID 30828987, 2019). "IL6 is positively associated with endometrial cancer risk in the obese population (ORQ4 vs. Q1 = 3.979, 95% CI 1.184–13.375, p = 0.026), while the same is not true when the entire population is considered (ORQ4 vs. Q1 = 0.471, 95% CI 0.301–0.736, p = 0.001; adjusted p = 0.007)." (PMID 38339282, 2024). "Similarly, combining IL-6, IL-8, and Monocyte counts enhanced the accuracy of assessing endometrial cancer risk with deep myometrial invasion." (PMID 38464838, 2024). "As part of the conducted case–control study, an attempt was made to establish the relationship between CRP, IL-6, IL-1RA (interleukin 1 receptor antagonist), and the degree to which these variables are associated with the risk of obesity and endometrial cancer." (PMID 35628566, 2022). "So we speculate the rs118050317 C allele of NINJ2 through regulate the IL-6 expression to influence the ERK-NF-κB signaling pathway of endometrial cancer growth." (PMID 33397383, 2021). "Dossus et al18 conducted a nested case‐control study of patients with endometrial cancer to determine the risk of endometrial cancer, and they found that the inflammation factor cytokines (especially IL‐6, TNF receptor, and C peptide) had an odds ratio of 1.62 for developing endometrial cancer." (PMID 32196750, 2020). "This study sought to investigate whether the IL4, IL6 two gene genetic variants were associated with susceptibility to endometrial cancer (EC) in Hainan Chinese Han women by a hospital‐based study." (PMID 30828987, 2019). "In conclusion, the rs1524107 (T/C) and the rs2066992 (T/G) in IL6 gene seem to be relevant to increased susceptibility to endometrial cancer, which suggests IL6 may play a role in EC, however, in IL4 gene, we did not found any SNPs were imposed significant with EC risk." (PMID 30828987, 2019).
endometrial cancer (continued). "In a mouse model of endometrial cancer, the main factors involved in this process are G-CSF, IL-6 and estradiol." (PMID 40136652, 2025). "In terms of inflammatory factors, this study found that endometrial cancer had higher mRNA expression of IL-6, IL-8 and IL-17, and higher levels of IL-6 protein than control." (PMID 40041148, 2025). "Pro‐inflammatory adipocytokines such as leptin and IL‐6 contribute not only to cancer development but also to endometrial cancer progression through multiple mechanisms." (PMID 40642843, 2025). "In mouse models of cervical and endometrial cancers, levels of G-CSF, IL-6 and estradiol contributing to MDSC generation are significantly increased." (PMID 40136652, 2025). "While CCDC68 acts as a pro-carcinogenic factor in IL-6-stimulated endometrial cancer cells, it also exhibits tumor-suppressor properties in pancreatic ductal adenocarcinoma." (PMID 40547309, 2025). "It secretes proinflammatory cytokines, such as tumor necrosis factor-alpha (TNF-α) and interleukin-6(IL-6), that promote a chronic inflammatory condition that facilitates the development of endometrial cancer." (PMID 41383623, 2025). "The study demonstrated an association between the presence of TNF-α, TNF receptors 1 and 2, IL-6, and C-reactive protein (CRP) and an increased risk for endometrial cancer in postmenopausal women." (PMID 41050662, 2025). "Correlation between increased Micrococcus abundance and IL-6 and IL-17 micro-RNA (mRNA) levels in endometrial cancer patients." (PMID 41050662, 2025). "Another study showed that IL-6 indirectly stimulates the proliferation, migration, and invasion of endometrial cancer cells and downregulates the expression of protooncogenes in cancer cells." (PMID 41050662, 2025). "Elevated circulating levels of certain pro-inflammatory cytokines, including interleukin-6 (IL-6), interleukin-8 (IL-8), and tumor necrosis factor-α (TNF-α) have been associated with an increased risk of endometrial cancer." (PMID 40877024, 2025). "In comparison to normal endometrium used as a reference or calibrator, the expressions of all the adipocytokines—adiponectin, leptin, IL6, and TNFα—were found to be much higher in endometrial cancer tissue." (PMID 40642843, 2025). "Interleukin-6 (IL6) facilitates immune escape in endometrial carcinoma (EC) by inducing mtDNA leakage and activating the cGAS-STING pathway." (PMID 39949780, 2025). "In endometrial cancer cells, E2 can augment IL-6 production, and it is suggested that this occurs through the NFκB pathway." (PMID 39000334, 2024). "The most well-known traditional activator of the JAK/STAT3 pathway is interleukin-6 (IL-6), indicated as the most significant ligand with carcinogenic potential, which also contributed to endometrial cancer development." (PMID 39188680, 2024). "A recent report implicated YAP in inducing expression of the pro-fibrotic interleukin IL-6 in the context of endometrial cancer." (PMID 37874141, 2023). "Cytokines were more abundant in cells derived from primary tumours than from metastatic sites (p < 0.001 for IL-6) or endometrial cancer cell lines (p < 0.001 for IL-6)." (PMID 34951691, 2022). "•Ulipristal acetate induced apoptosis in endometrial cancer cells and activated oncostatin M, IL-6, IL-8 known as proinflammatory cytokine." (PMID 35036597, 2022). "In the multivariate regression analysis, BMI, leptin, and IL-6 were independent predictive variables of T, N, and M status in endometrioid type I endometrial cancer patients." (PMID 35053431, 2022). "The multivariate regression analysis showed that BMI, leptin, and IL-6 were predictive for T, N, and M status in the type I endometrial cancer patients." (PMID 35053431, 2022). "No studies have examined the influence of circulating levels of IL‐6 or TNF‐α on prognostic outcomes for endometrial cancer survivors." (PMID 35174651, 2022).
endometrial cancer (continued). "Micrococcus abundance in the endometrial microbiota is positively correlated with IL-6 and IL-17 mRNA, which supports a plausible link between the endometrial microbiota and inflammation in women with endometrial cancer." (PMID 36303679, 2022). "We found that BMI, leptin, and IL-6 significantly correlated with T status, N status, and M status among endometrioid type I endometrial cancer patients." (PMID 35053431, 2022). "We also observed a significant linear correlation between circulating ROS values and BMI, leptin, and IL-6 in the type I endometrial cancer patients." (PMID 35053431, 2022). "In endometrial cancer, both IL-6 and TNF-α have been reported to be overexpressed, and to play a role in cancer growth and metastasis, partly also by inducing ROS and subsequent DNA damage." (PMID 35053431, 2022). "By sub-dividing the patients according to endometrial cancer subtypes, we found that among the type I endometrial cancer patients, BMI, leptin, and IL-6 significantly correlated with T status, N status, and the presence of distant metastases (stage IV)." (PMID 35053431, 2022). "One study reported that 17β-estradiol promotes endometrial cancer proliferation and progression via activation of the IL-6 signaling pathway, and another revealed that OSM, a member of the IL-6 family, enhances endometrial cancer invasion and angiogenesis." (PMID 35036597, 2022). "Immunological factors such as TNF-α, TNF receptors 1 and 2, IL-6, and C-reactive protein (CRP) have been identified as inflammatory variables associated with an increased risk of endometrial cancer in postmenopausal women." (PMID 35628566, 2022). "In detail, three large case studies demonstrated a relationship between the circulating levels of TNF-α, IL-6, IL-1α, and C-reactive protein (CRP) and elevated risk of endometrial cancer." (PMID 35053431, 2022). "IL-6 has been shown to stimulate aromatase activity in adipose tissue and in endometrial cancer stromal cells, which then increases estrogen levels." (PMID 34357126, 2021). "Various MDSC-targeting strategies have been evaluated in murine models of uterine cervical and endometrial cancers, such as anti-Gr-1 antibody, anti-IL-6 antibody, COX-2 inhibitor, STAT3 inhibition, and splenectomy." (PMID 33946532, 2021). "The study found an implication of the ERK-NF- κB pathway as a critical mediator of IL-6 production and its potential role in targeted treatment for patients with endometrial cancer." (PMID 33799622, 2021). "It has also become apparent that miR-361 can downregulate the mRNA expression of IL-6 and IL-8 in endometrial cancer cells through targeting TWIST." (PMID 33522952, 2021). "The analysis also showed that important signaling pathways such as CREB, Wnt, FGF, IL-6, and ERK/MAPK, and that of the endometrial cancer, and cell cycle were implicated." (PMID 34040530, 2021). "In the case of IL-6, CAFs promote endometrial cancer cells proliferation via activation of the IL-6/STAT-3/c-Myc axis, both in vitro and in vivo models." (PMID 34501347, 2021). "Patients with endometrial cancer have high levels of IL-6 and nuclear factor-kB (NF-kB), a cellular transcription factor that activates several genes involved in the inflammatory and immune response." (PMID 34357126, 2021). "The endometrial cancer microenvironment fosters a feedback loop of IL-6, aromatase, and in-situ estrogen elevations, which promotes tumorigenesis." (PMID 33415077, 2020). "Adipose-derived IL-6 can promote the proliferation, invasion and angiogenesis of endometrial cancer cells by activating the JAK/STAT3 signaling pathway." (PMID 31440472, 2019). "Studies have confirmed that IL-6 is closely related to the occurrence of a variety of tumors, including endometrial cancer." (PMID 31440472, 2019). "CAFs secrete numerous pro-tumorigenic cytokines that include interleukin-6 (IL-6), which can be isolated from endometrial cancer tissues and promote cell proliferation." (PMID 30935077, 2019).